NRAS (NRAS proto-oncogene, GTPase)
Diseases named in the same sentence as NRAS in open-access papers (continued):
Sharing a sentence is not in itself a finding about the gene and the disease.
RASopathy (33 papers, 2015 to 2026). Developmental syndromes caused by germline mutations (or in rare cases by somatic mosaicism) in genes that alter the Ras subfamily and mitogen-activated protein kinases that control signal transduction. "Nevus spilus-type congenital melanocytic nevi have also been found to harbor an activating NRAS variant, though this entity is a genotypically and phenotypically distinct class of mosaic RASopathies." (PMID 41523454, 2025). "The identification of mutations in HRAS and NRAS in NS provides insight into the pathophysiology of this hamartoma, defining NS as a mosaic RASopathy." (PMID 34208656, 2021). "In mosaic RASopathies, NRAS p.Q61R mutations have been identified in a patient with Schimmelpenning syndrome, patients with neurocutaneous melanosis, and patients with cutaneous–skeletal hypophosphatemia syndrome." (PMID 31511039, 2019). "The boy with GCMN carried NRAS mutation at codon 61, in addition to the characteristic facial features relevant to RASopathies." (PMID 30792691, 2019). "In agreement with the previous finding, case-I had mutated NRAS at codon 61, along with characteristic facial features relevant to RASopathies." (PMID 30792691, 2019). "Further, we compared the specific variants observed here to variants in HRAS, KRAS, or NRAS previously reported as pathogenic for RASopathies." (PMID 30500825, 2018). "Multiple congenital melanocytic naevi (CMN) is a rare mosaic RASopathy, caused by postzygotic activating mutations in NRAS." (PMID 26286459, 2015). "NRAS G60E is a mildly activated mutantthat causes RASopathy in humans and fish." (PMID 37272594, 2023). "The affected residues (p.Gly23, p.Thr68, p.Gln71) exhibit high evolutionary conservation across RAS family GTPases associated with RASopathies, including HRAS, NRAS, KRAS, and RRAS2." (PMID 41517739, 2026). "In a review of patients with mosaic RASopathies including ECCL, the majority of ECCL patients had mutations in the KRAS gene, with one patient presenting with an NRAS gene." (PMID 41283481, 2025). "In fact, double-knockouts of HRAS and NRAS display a RASopathy-like phenotype, which contrasts to the assessment of the same double-knockout 25 years ago, i.e. at a time when many other RAS knockout studies were conducted and evaluated." (PMID 41248180, 2025). "Many of the RASopathy-associated genes are in gene families: RAF (BRAF and RAF1), RAS (HRAS, KRAS, MRAS, NRAS, RIT1, and RRAS2), MAP2K (MAP2K1 and MAP2K2), and SOS (SOS1 and SOS2)." (PMID 40496714, 2025). "Our data identifies the concomitant ablation of HRAS and NRAS as a new molecular alteration capable of triggering the development of RASopathy phenotypes in mice through a mechanism involving the hyperactivation of KRAS-dependent signaling." (PMID 38886790, 2024). "All variants are registered as pathogenic in ClinVar, and the variants that are homologous to p.Gly23Val have been reported to cause RASopathy in KRAS, HRAS, and NRAS." (PMID 38601074, 2024). "Here, we demonstratelight-induced activation of Protein Kinase A and a RASopathy mutantof NRAS in the zebrafish embryo using a new light-activated aminoacid." (PMID 37272594, 2023). "Found in perhaps 1:1000 new births, RASopathies are associated with variants in genes encoding multiple RAS pathway components including KRAS, NRAS, BRAF, RAF1, and SHP2." (PMID 33855281, 2021). "In a wide spectrum of RAS-related disorders, recently called RASopathies, somatic RAS mutations, especially somatic NRAS mutation at codon 61 (p.Q61R/K), have been identified in a variety of human malignancies." (PMID 31511039, 2019). "Postzygotic KRAS, HRAS, NRAS, and FGFR1 mutations result in a group of mosaic RASopathies characterized by related developmental anomalies in eye, skin, heart, and brain." (PMID 30891959, 2019). "Some of these genes increase predisposition to cancer, for example, in rasopathies, and BRAF, KRAS, HRAS, NF1, NRAS PTPN11, RAF129." (PMID 27080396, 2016).
RASopathy (continued). "Given the relation to mosaic RASopathies involving hyperactivation of the RAS-MAPK-MEK pathway, MEK inhibitors have shown some initial promise in case reports of congenital melanocytic lesions with activating genetic variants in NRAS and mosaic BRAF fusions." (PMID 41523454, 2025). "The RASopathies, collectively, are a spectrum of genetic syndromes caused by mutations in genes involved in the RAS/ mitogen-activated protein kinase (MAPK) pathway, including but not limited to PTPN11, NRAS, KRAS, HRAS, BRAF, and MAP2K1." (PMID 39385823, 2024). "In this report, we show that simultaneous removal of both HRAS and NRAS in mice leads to the generation of a RASopathy-like phenotype in the very small percentage of adult animals that are able to survive the perinatal period and reach adulthood in the absence of both HRAS and NRAS." (PMID 38886790, 2024). "Interestingly, in addition to patients with KRAS, NRAS, and BRAF mutations, we found that MM exhibited a long tail of alterations in rare, congenital RAS-pathway-related diseases, known as the “Rasopathies”." (PMID 35768438, 2022). "RASopathies represent a family of mostly autosomal dominant diseases that are caused by missense variants in the rat sarcoma viral oncogene/mitogen activated protein kinase (RAS/MAPK) pathway including KRAS, NRAS, BRAF, RAF1, and SHP2." (PMID 33855281, 2021). "We show that spontaneous colony formation in CMML functionally covers NRAS and CBL, the most frequent RASopathy gene mutations (>10%), and thus may be considered as a functional parameter for RAS-pathway hyperactivation in these patients." (PMID 32842710, 2020). "A possible mechanism underlying these abnormalities could be related to overactivity of the G‐protein function of NRAS in many pathways, supported by data from germline RASopathies, but further molecular work will be required to elucidate the molecular basis." (PMID 26286459, 2015). "For example, RASopathies, such asNoonan syndrome, Neurofibromatosis 1 and Leopard syndrome, are a subtype ofdevelopmental diseases characterized by mutations in genes encoding for components ofthe Ras/MAPK pathway (NF1, PTPN1, SOS1, RAF1,KRAS, NRAS, SHOC2, CBL)." (PMID 29719609, 2018). "More than 90% of JMML cases harbor germline or somatic mutations in one of five canonical driver genes-PTPN11, NRAS, KRAS, NF1, or CBL-establishing JMML as the prototypical malignant manifestation of RASopathy biology." (PMID 42193013, 2026). "Our data uncovers a new, previously unidentified mechanism capable of triggering a RASopathy phenotype in mice as a result of the combined removal of HRAS and NRAS." (PMID 38886790, 2024). "Because of their functional significance RAS signaling pathway components including NRAS, KRAS, NF-1, PTPN11, and CBL were summarized as RASopathy genes within one category." (PMID 32344757, 2020). "In addition to the well-characterized NRAS, KRAS, and BRAF genes, our study revealed that the germline Rasopathy genes represent a long tail of somatic alterations linking MM to these rare, congenital RAS-pathway-related diseases." (PMID 35768438, 2022). "It is therefore reasonable that, although HRAS and NRAS are not critically needed for survival, their absence in the DKO is an essential mechanistic driver of the appearance of the defective, non-lethal RASopathy phenotypes described here." (PMID 38886790, 2024).
glioma (32 papers, 2012 to 2025). A benign or malignant brain and spinal cord tumor that arises from glial cells (astrocytes, oligodendrocytes, ependymal cells). "Mutations in KRAS, HRAS and NRAS are known in gliomas and are often concomitant with BRAF mutations and fusions." (PMID 37490467, 2023). "Overexpression of miR-143 decreased glioma cell migration, invasion, tube formation and slowed tumor growth and angiogenesis in a manner associated with NRAS down-regulation in vitro and in vivo." (PMID 26646588, 2016). "RAS mutations were identified in four gliomas with three KRAS mutations and one NRAS mutation in one anaplastic oligodendroglioma, two anaplastic astrocytomas (IDH wild-type in each), and one ganglioglioma." (PMID 34525976, 2021). "In the current study, we sought to determine the expression and function of NEAT1, let-7e and NRAS in glioma tissues and GSCs." (PMID 27556696, 2016). "NRAS protein levels in normal brain tissues, glioma tissues and GSCs were investigated by immunohistochemistry and Western blot." (PMID 27556696, 2016). "NRAS localized to the cytoplasm and was upregulated in glioma tissues compared with normal brain tissues." (PMID 27556696, 2016). "Whether NRAS protein is a viable clinical therapy target for patients with glioma remains to be investigated." (PMID 27556696, 2016). "MiR-143 was also demonstrated to directly target NRAS and may function as a tumor-suppressor in glioma." (PMID 26646588, 2016). "Thus, therapies targeting the NEAT1/let-7e/NRAS axis may be promising options for the treatment of human glioma." (PMID 27556696, 2016). "This upregulation subsequently activates the NRAS/MEK1/ERK1–2 signalling pathway by sequestering miR-502–5p, thereby promoting glioma cell proliferation." (PMID 40469294, 2025). "EIF4A3 activates the NRAS/MEK1/ERK1–2 signalling pathway by upregulating the expression of circASAP1, which significantly promotes glioma reproduction and TMZ resistance." (PMID 40469294, 2025). "Overall, this study indicated that PHF20 is a pivotal upstream gene that influences the occurrence and development of glioma by regulating a series of tumor-related genes, like FEN1, CCL3, PLCB1, NRAS and PIK3s, and involved in apoptosis signaling pathways." (PMID 29033691, 2017). "It affects the occurrence and development of glioma by regulating a series of tumor-related genes, such as FEN1, CCL3, PLCB1, NRAS and PIK3s, and activation of apoptosis signaling pathways." (PMID 29033691, 2017). "Similarly, the Western blot revealed greater protein levels of NRAS in glioma tissues and GSCs than in normal brain tissues and non-GSCs." (PMID 27556696, 2016). "Indeed, we found six and ten significant pathways in LGG (Brain Lower Grade Glioma) and UCEC (Uterine Corpus Endometrial Carcinoma) (adj P (Cox) < 0.05) respectively, invariably involvingPIK3CA along with different combinations of other oncogenes (e.g.NRAS,KRAS) interfaces." (PMID 36569594, 2021).
non-small cell lung carcinoma (30 papers, 2010 to 2025). A group of at least three distinct histological types of lung cancer, including non-small cell squamous cell carcinoma, adenocarcinoma, and large cell carcinoma. "■Salicylic acid derivative;■Investigational for non-small-cell lung carcinoma (phase 2);■Serine/threonine-protein kinase mTOR modulator; GTPase NRas antagonist." (PMID 40298549, 2025). "Three different isoforms of RAS proteins have been identified to date (KRAS, NRAS, HRAS) and mutations in KRAS are frequently found in human cancers, among which the Non-Small Cell Lung Cancer (NSCLC)." (PMID 36358848, 2022). "Here, we report our experience using next generation sequencing (NGS) to examine AKT1, BRAF, EGFR, ERBB2, KRAS, NRAS, and PIK3CA genes in 1006 non-small cell lung cancers in a clinical diagnostic setting." (PMID 29228562, 2017). "The IDH1 and IDH2 mutations are also present in 0.9% of colorectal cancer, associated with the BRAF V600E mutation, in 0.5% of non-small cell lung carcinoma (NSCLC), co-existing with KRAS mutations and in melanoma, occurring with NRAS mutations." (PMID 39123479, 2024). "A recent study conducted in over 350 Vietnamese patients with non-small cell lung cancer (NSCLC) from four hospitals revealed the presence of EGFR mutations in 35% of cases, KRAS mutations in 23%, ALK rearrangements in 7%, ROS1 rearrangements in 3%, BRAF mutations in 2%, and NRAS mutations in 0.6%." (PMID 38317094, 2024).
acral melanoma (29 papers, 2014 to 2026). "Another Chinese study included 311 samples of acral melanoma, and only one sample (1.4%) was observed NRAS mutation in 70 assessable samples." (PMID 41492362, 2026). "BRAF and NRAS are the most commonly mutated oncogenes in acral melanomas, though they occur less frequently than in sun-exposed melanomas, while KIT mutations are more prevalent in ALM." (PMID 40362334, 2025). "BRAF and NRAS mutations are common in acral melanocytic nevus, whereas acral melanoma shows lower rates of KIT, NF1, BRAF, and NRAS mutations and remarkable copy number variations in genes such as CCND1, CDK4, hTERT, PAK1, and GAB2." (PMID 35997352, 2022). "NRAS (26.7%, 4/15) was the gene with the highest mutation frequency in acral melanoma, including 2 p.Q61K and 2 p.Q61R mutation." (PMID 35688842, 2022). "In Caucasians population, the rate of acral melanoma with NRAS mutations is about 15–20%." (PMID 41492362, 2026). "While in Asian population, the frequency of NRAS mutations in acral melanoma seems to be lower." (PMID 41492362, 2026). "Overall, NRAS mutations were present in 29% of acral lentiginous melanomas." (PMID 33917086, 2021). "Considering we detected no recurrent non-V600E BRAF, KIT, or NF1 mutations in naevi, this may imply that acral melanomas harboring these mutations arise primarily de novo, whereas BRAF V600E or NRAS Q61 mutant acral melanomas may more frequently arise from pre-existing naevi." (PMID 30995742, 2019). "Strikingly, the study of acral melanoma also identified recurrent driver mutations in RTK/RAS signaling genes, including PTPN11, KIT, NF1, KRAS, and NRAS, all of which are recurrent in human AML (and commonly associated with NPM1c mutations)." (PMID 40773291, 2025). "In acral melanoma, BRAF (9%), NRAS (17%), KRAS (8%), KIT (19%), and NF1 (7%) mutations were detected." (PMID 39564955, 2024). "KIT mutations were detected exclusively in three acral lentiginous melanomas (10%); in one case it was found in association with a NF1 mutation and in another with a NRAS mutation." (PMID 33917086, 2021). "TERT promoter mutations were found in 4 cases (13%): two acral lentiginous melanomas also harbored a BRAF mutation, another a NRAS mutation, while a nodular melanoma harbored a NF1 mutation." (PMID 33917086, 2021). "In acral melanoma, BRAF and NRAS are still the most frequent mutations present (although less frequent than in non-acral cutaneous melanoma), followed by NF1 and KIT mutations." (PMID 30995742, 2019). "In our previous study of adjuvant PD‐1 inhibitors for acral melanoma, we enrolled eight patients with NRAS mutation and 23 patients without NRAS mutation." (PMID 41492362, 2026). "In Taiwan, NRAS/KRAS mutations, cell cycle aberrations, increased copy numbers in antiapoptotic genes BIRC2, BIRC3, and BIRC5, and the amplification of receptor tyrosine kinase genes were significantly enriched in acral melanoma." (PMID 35997352, 2022). "As a result, the activation of YAP in turn upregulates the expression of NRAS and BRAF genes, promoting the development of acral melanoma." (PMID 37894888, 2023). "When it comes to acral melanoma, cyclin D1 has been reported to be overexpressed, resulting in constitutively activated MAPK signaling pathway without NRAS or BRAF mutations." (PMID 35484605, 2022).
gastric cancer (27 papers, 2009 to 2025). A primary or metastatic malignant neoplasm involving the stomach. "This study provides more data support for clinical research on KRAS/NRAS/BRAF mutation in CRCs or gastric cancers." (PMID 30416987, 2018). "There are few studies on the mutations rate of KRAS/NRAS/BRAF in gastric cancer." (PMID 30416987, 2018). "Gastric cancer cells were stimulated to proliferate and metastasize by CircDLST through sponging miR-502-5p, which activated the NRAS/MEK1/ERK1/2 signaling cascade." (PMID 35842702, 2022). "Low miR-502-3p expression accelerates proliferation as well as migration for gastric cancer cells via NRAS/MEK1/ERK1/2 axis." (PMID 33928106, 2021). "In gastric cancer, miR-502-5p inhibited the growth and metastasis of gastric cancer cells in vitro and in vivo by blocking the NRAS/MEK1/ERK1/2 signal pathway." (PMID 33758619, 2021). "Similarly, circDLST activates NRAS/MEK1/ERK1/2 pathway to aggravate gastric cancer progression via sponging miR-502-3p." (PMID 36755807, 2023). "Furthermore, a link between DLST and ERK/MAPK signaling pathways was previously suggested, as circDLST was shown to sponge with microRNA, activating the NRAS/MEK/ERK signaling in gastric cancer." (PMID 36634214, 2023). "Furthermore, miR-26a improves the sensitivity of gastric cancer cells to cisplatin-based chemotherapies by targeting NRAS and E2F245." (PMID 30258124, 2018). "KRAS/NRAS/BRAF mutations were not significantly related to patients' age analyzed by Student's t-test or gender analyzed by Chi-square test in gastric cancer." (PMID 30416987, 2018). "The main purpose of this study is to investigate the mutation status and distribution of KRAS/NRAS/BRAF in Chinese colorectal and gastric cancers, and to explore the histopathological changes and related immunohistochemical marker changes caused by these mutations." (PMID 30416987, 2018). "No KRAS or NRAS mutation was found in gastric cancer in this study." (PMID 30416987, 2018). "Although HER2 is a well-established oncogene in breast and gastric cancers, it has recently gained recognition as a clinically significant biomarker in approximately 3–5% of CRLM, particularly among KRAS/NRAS wild-type tumors." (PMID 40805233, 2025). "The gastric cancer genome is characterized by focal amplification of oncogenes, including receptor tyrosine kinases, such as ERBB2 (HER2), EGFR, ERBB3, VEGF-A, KRAS/NRAS, MET, JAK2, and PD-L1/PD-L2." (PMID 38733489, 2024). "In addition, we selected the serum of 80 ECs, 80 HCCs, and 80 LCs and measured the titer of four TAAbs (anti-MFGE8, anti-NRAS, anti-PTP4A1, anti-RRAS2) by ELISA to verify the specificity of four TAAbs in gastric cancer." (PMID 33718231, 2021). "In all 34 gastric cancer samples, neither KRAS nor NRAS mutation was detected, and only 1 sample (2.9%) was detected to have a mutation in BRAF exon 15 codon 600 600Glu." (PMID 30416987, 2018). "For absence of NRAS, KRAS and BRAF mutation, SGC7901 and BGC823 gastric cancer cells were relative resistance to AZD6244 in vitro." (PMID 26567773, 2015). "Immunoblot analysis of RAS proteins revealed that the expression of KRAS was increased in KRAS-amplified gastric cancer cells (HSC45, SH101P4 and MKN1), while neither NRAS nor HRAS were highly expressed (data not shown)." (PMID 19545448, 2009).